CRP (C-reactive protein)
Diseases named in the same sentence as CRP in open-access papers (continued):
Sharing a sentence is not in itself a finding about the gene and the disease.
Obesity (continued). "Dose–response pattern was observed across the BMI categories from normal weight to overweight to obesity for fat distribution, chewing muscle extent, periodontal probing depth, number of teeth, and inflammatory markers such as CRP and fibrinogen." (PMID 36694084, 2023). "As a marker of obesity, the level of hs-CRP is significantly elevated in the obese individual, and positively correlated with BMI obesity." (PMID 37033234, 2023). "Inflammatory markers, including C-reactive protein, interleukin-6, and tumor necrosis factor, are positively related to obesity and the aggravation of insulin resistance." (PMID 36803382, 2023). "According to several reports, elevated CRP levels have been directly correlated with conditions like obesity, dyslipidemia, hyperglycemia, and insulin resistance." (PMID 37887410, 2023). "The condition of obesity leads to the development of an inflammatory environment in the body, characterized by elevated levels of various markers such as C-reactive protein, interleukin-6, and tumor necrosis factor-α in the bloodstream." (PMID 37109333, 2023). "Despite the obesity-related increase in GCF CRP levels, the clinical measures of gingival inflammation and GCF inflammatory cytokine levels were not significantly increased." (PMID 38138192, 2023). "Given these different biological actions, it is unsurprising that elevated plasma CRP levels represent one of the strongest and independent prognostic factors for the development of cardiovascular disease in obesity." (PMID 36674022, 2023). "Several clinical studies have established a significant correlation between elevated levels of IL-8 and CRP and conditions such as obesity, sarcopenia, and osteoporosis." (PMID 37525169, 2023). "Several studies in people with impaired glucose tolerance and impaired fasting glucose have verified that CRP is positively correlated with insulin resistance, obesity, and blood triglyceride levels." (PMID 37660067, 2023). "High EAT volume was more common in men with higher BMI and waist circumference, obesity, hypertension, higher levels of CRP and s-triglycerides, and lower levels of s-HDL (all p < 0.05)." (PMID 38173787, 2023). "Future studies measuring the levels of sex hormones and body fat compositions along with ANGPTL8 levels in adolescents are required to validate the observed relationships that ANGPTL8, chemerin, leptin, and CRP have with obesity." (PMID 38189043, 2023). "In summary, moderate intensity walking is an effective therapeutic expected improving percent body fat, TNF- and hs CRP in postmenopausal women with obesity." (PMID 37978254, 2023). "In our study, HFD-induced obesity promoted a significant increase in CRP only in APP/PS1 mice at both 6 and 10 months of age." (PMID 37686722, 2023). "The adjusted parallel mediation model indicated that the association between the obesity-related DP and overall cancer was fully mediated by five inter-mediators (BMI, WHR, HDL, C-reactive protein, and triglycerides)." (PMID 37424008, 2023). "Previous studies reported implant- and patient-related risk factors for PJI following revision arthroplasty, including adverse metal reaction, use of megaprosthesis, implant loosening, elevated serum CRP prior to revision surgery, obesity, and male sex." (PMID 37175046, 2023). "Previous studies showed some Firmicutes were reduced in Cystic Fibrosis in children, and high amounts of some Firmicutes were related with obesity in children and C-reactive protein, which is an inflammation marker." (PMID 37239112, 2023). "After processing the data we extracted from the included studies, we pointed out that CRP had a better performance in differentiating the MetS group from the simple obesity control group than hsCRP." (PMID 38001962, 2023). "Our data also showed that obesity has an unfavorable influence on the association between blood and GCF CRP levels; the association was more pronounced in the obese individuals." (PMID 38138192, 2023).
Obesity (continued). "We have also analyzed the relationships between plasma concentrations of sP2X7R and the most common plasmatic inflammatory markers associated with the chronic low-grade inflammation present in obesity, such as CRP, TNFα and IL-6." (PMID 38069064, 2023). "Persons who suffer from obesity or hyperinsulinemia tend to produce a higher amount of CRP from adipocytes along with other inflammatory markers." (PMID 37008812, 2023). "Based on previous studies, minor-elevation (1 μg/ml) and moderate-elevation (2.5 μg/ml) dosages of CRP were used to represent the clinical features of a chronic inflammation process in obesity and in chronic diseases." (PMID 37929799, 2023). "High levels of inflammatory markers such as TNF-alfa, IL -1beta, IL-6, and CRP are elevated in both obesity and PTSD, indicating a common pathological link." (PMID 37374323, 2023). "Individuals with depression or obesity have been found to exhibit elevated levels of inflammatory biomarkers such as C-reactive protein compared to healthy controls (HCs)." (PMID 37692303, 2023). "For instance, circulating levels of chemerin strongly correlated with markers of inflammation, such as TNF-α, IL-6, and C-reactive protein, in the context of obesity." (PMID 36883565, 2023). "Obesity and age-related increases in inflammatory cytokines (e.g. TNF-α, IL-6, and CRP) cause exacerbated danger-associated molecular patterns and immunosenescence, thereby increasing morbidity and mortality." (PMID 37372149, 2023). "Among patients who developed HAI, male sex, obesity, lower oxygen saturation, lymphopenia, and higher concentrations of C-reactive protein (CRP), lactate dehydrogenase (LDH), and ferritin at hospital admission were present." (PMID 37508204, 2023). "The CRP levels have been demonstrated to correlate positively with obesity, blood pressure, the triglyceride levels, fasting blood glucose, and insulin sensitivity." (PMID 36674022, 2023). "A double-blinded, randomized clinical trial was conducted in 76 adults with overweight or obesity (BMI 28 to 40) and low-grade inflammation (high-sensitivity C-reactive protein (hs-CRP) between 2 and 10 mg/L)." (PMID 37239916, 2023). "There are few studies concerning the relationship between obesity and CRP, taking into account smoking status." (PMID 37375693, 2023). "We selected CRP as a marker of chronic inflammation in the human body to explore its mediating role in obesity-induced PC." (PMID 36816931, 2023). "In this research, we use BMI in place of obesity and use CRP instead of chronic inflammation in people." (PMID 36816931, 2023). "A previous prospective cohort study of 3,891 English community-dwelling older adults showed that higher CRP represented a partial mediator of the relationship between obesity and subsequent overall depressive symptoms." (PMID 36462595, 2023). "The proportion of subjects with obesity increased substantially at medium and high CRP levels; HTG showed a similar but weaker trend, but such a change was not conspicuous for depression." (PMID 38455932, 2023). "ACE1 activity was also increased in the supernatant of a T cell culture in individuals with obesity with a high-sensitivity CRP level of >3 mg/dL." (PMID 37725526, 2023). "In older adults with obesity and diabetes, 6 months of aerobic exercise training decreased CRP and IL-18 with an increase in the anti-inflammatory cytokine IL-10." (PMID 37372149, 2023). "We have reported in previous studies that high postoperative CRP level is correlated with obesity and contributes to a poor prognosis." (PMID 37344511, 2023). "The present study demonstrates that both retro walking and forward walking can help alleviate CRP level and obesity." (PMID 37008812, 2023). "In our study of 1,630 Chinese adults, we found that high HbA1c levels and overweight/obesity were independent predictors of hs-CRP elevation, even after considering several traditional confounding factors." (PMID 37215204, 2023).
Obesity (continued). "Among the various biomarkers related to obesity and MetS, adiponectin, leptin, C-reactive protein (CRP), and cytokines such as interleukins (ILs) -1 and -6 stand out." (PMID 37571250, 2023). "Among boys (mean age 11.06 years), girls (mean age 16 years), and women (aged 40–50 years) affected by obesity, 3 months of HIIT was more effective than aerobic training for decreasing CRP and related cardiovascular risk factors." (PMID 37608837, 2023). "Dysbiosis also affects the secretion of inflammatory cytokines, and it is known that obesity is associated with high levels of IL-6, TNF-alpha, and C-reactive protein." (PMID 37374323, 2023). "This is due to the fact that poor oral hygiene, in addition to triggering an inflammatory response within the oral cavity, also results in an increase in C reactive protein levels, which has been related to obesity." (PMID 36900046, 2023). "The synergistic effect of HTG with depression was found to be most prominent at a medium CRP level (1–3 mg/L), while for obesity, the effect was observed across all CRP levels examined." (PMID 38455932, 2023). "Obesity increases CRP levels thus exacerbating the inflammatory process across the periconceptional period." (PMID 36520252, 2023). "During the last decade, several studies have suggested that obesity is associated with an inflammatory process characterized by increased plasma levels of proinflammatory cytokines such as TNF-α, IL-6, and C-reactive protein." (PMID 36902133, 2023). "Hs-CRP is a marker of low-grade inflammation, and it is chronically elevated in patients with atherosclerosis and obesity." (PMID 36797524, 2023). "In general, CRP and measures of obesity, chronic hyperglycemia and insulin resistance displayed tendencies toward more marked suppression or attenuated elevation of several inflammatory markers (Supplement S4)." (PMID 37400734, 2023). "Like obesity, salivary CRP is suggested to be a predictor of pediatric acute respiratory illness, more importantly in pediatric pneumonia." (PMID 36831972, 2023). "Studies have confirmed a significant increase in CRP and insulin concentrations in the saliva of children with obesity." (PMID 36831972, 2023). "Subjects with obesity also had increased hepatic-iron concentration, circulating ultrasensitive C-reactive protein (CRP), fasting triglycerides, serum uric acid, serum transferrin, and total iron-binding capacity (TIBC)." (PMID 36902180, 2023). "HFD-induced obesity was related with growing age to a significant increase in CRP, a marker of peripheral inflammation, only in the fasted plasma of APP/PS1 mice at 6 and 10 months of age in comparison with 3-month old mice on a HFD." (PMID 37686722, 2023). "Twelve weeks of high-intensity indoor cycling (80%–95% HRmax, 3 sessions/week) was an effective stimulus for improving the aerobic capacity and reduce the levels of the CRP in women (aged 40–60 years) with obesity." (PMID 37608837, 2023). "Specifically, increased levels of inflammatory markers, including CRP, have been detected in children, adolescents, and adults with obesity and MetS." (PMID 36920931, 2023). "Relative to participants with normal weight, those with obesity were more likely to have higher levels of CRP." (PMID 36462595, 2023). "CRP can also increase blood–brain barrier paracellular permeability and enter the brain parenchyma in mice with adult-onset obesity in a dose-dependent manner." (PMID 37873776, 2023). "Individuals with obesity display a two to three-fold increase in circulating levels of C-reactive protein (CRP), tumor necrosis factor-alpha (TNF-alpha), and interleukin-6 (IL-6), when compared to their normal weight counterparts." (PMID 37139450, 2023). "Inflammatory mediators, including chemokines and CRP, serve as biomarkers that report on aging, exercise, nutrition, and chronic diseases including atherosclerosis, diabetes, obesity, sarcopenia, and Alzheimer’s disease." (PMID 37603433, 2023).
Obesity (continued). "On the other hand, obesity is characterized by systemic, chronic, and low-grade inflammation, with an increase in C-reactive protein (CRP), Alpha 1-acid glycoprotein (AGP), and interleukin 6 (IL-6)." (PMID 36982031, 2023). "GlycA has been reported to be more sensitive and more stable than the more commonly used high sensitivity C-reactive protein, used as a gold standard marker of inflammation, and is elevated in obesity." (PMID 38111603, 2023). "Studies carried out in adults with obesity, hyperglycemia, and insulin resistance demonstrate parallel increases in their IL-6 and CRP concentrations with increasing insulin resistance." (PMID 37892418, 2023). "DII was significantly correlated with of obesity, and two different types of obesity were significantly correlated with hs-CRP and WBC levels." (PMID 36900791, 2023). "The link of circulating IL-6, CRP and leptin with obesity and metabolic abnormalities is well documented, with studies showing their positive association with different anthropometric parameters." (PMID 37529617, 2023). "There was a significant difference in hs-CRP values between at least two different obesity categories (p = 0.0001)." (PMID 37754594, 2023). "Evaluate how obesity affects coordination during locomotion using the CRP (continuous relative phase) method." (PMID 36991886, 2023). "The paralleled mediation analysis suggested that the association between the obesity-related DP and overall cancer is mediated by the body mass index (BMI), the waist-to-hip ratio (WHR), C-reactive protein, high-density lipoproteins (HDLs), and triglycerides." (PMID 37424008, 2023). "Individuals living with obesity also presented with elevated markers of inflammation in peripheral blood compared to lean controls, with increased acute phase reactant C-reactive protein (CRP) and erythrocyte sedimentation rate (ESR)." (PMID 37463992, 2023). "It has been suggested that individuals with an elevated BMI, particularly those with obesity, have elevated concentrations of serum inflammatory markers, such as C-reactive protein, tumour necrosis factor alpha (TNF-α), and interleukin 6 (IL-6)." (PMID 38097936, 2023). "Other studies showed that circulating levels of amyloid A protein, interferon-gamma (IFN-γ), interleukin-6 (IL-6), tumor necrosis factor alpha (TNF-α), and C-reactive protein (CRP) were prominently reduced in patients with obesity by CR." (PMID 37755259, 2023). "In our study, the hs-CRP level decreased by 72.59% after W-LHIT treatment, which confirmed that managing obesity can help reduce the risk of cardiovascular disease and comorbidities by inhibiting the inflammatory mechanism." (PMID 37033234, 2023). "Significantly higher levels of pre-operative WBC and CRP were observed in our obese patients, indicating the possibility of overweight/obesity-induced inflammation in these pregnant women." (PMID 37679736, 2023). "CRP, IL-6 and adiponectin levels were similar to other surveys in Greek metabolically unhealthy cohorts with obesity." (PMID 37529617, 2023). "One of the components of the pathogenesis of obesity is inflammation, and many inflammatory cytokines such as C-reactive protein, IL-6, and TNF-α play a vital role in the disease and are also commonly raised in seborrheic dermatitis patients." (PMID 37503468, 2023). "Obesity is considered a low-grade chronically inflamed state that presents higher levels of IL-6 and CRP in the body." (PMID 37566728, 2023). "Significant associations have been found between TGFβ1 levels and hepatic abnormalities such as steatosis, obesity, and CRP." (PMID 37626717, 2023). "Pro-inflammatory cytokines that are associated with obesity and aging include tumor necrosis factor α (TNF-α), interleukin 6 (IL-6), and C-reactive protein (CRP), which cause peripheral blood mononuclear cells to be in a pro-inflammatory state." (PMID 37372149, 2023).
Obesity (continued). "For instance, the clinically relevant differences at baseline inCOVID-19 patients were a higher body mass index, obesity, and test results showinghigher blood glucose, C-reactive protein, and lactic dehydrogenase levels." (PMID 38265317, 2023). "CRP has been shown to inhibit insulin signaling through Fcγ, and genetic elimination of CRP confers resistance to obesity and insulin resistance in rats." (PMID 37893085, 2023). "As serum CRP and obesity status are important predictors of cardiovascular risks in clinics, our observations underscore the need to take rare genetic factors into consideration to improve the delivery of precision medicine." (PMID 37493001, 2023). "In another study, children with overweight and obesity who participated in a school-based physical exercise study for 8 months showed a significant decrease in BMI z-score, C-reactive protein (CRP), and serum hepcidin, and a significant increase in serum iron." (PMID 37284649, 2023). "Low-grade inflammation persistent in obesity increases the amount of human C-reactive protein (CRP)." (PMID 37363537, 2023). "This is in accordance with the low prevalence of obesity and low CRP in the E4 group, since CRP, obviously, and obesity are also associated with inflammation." (PMID 37895304, 2023). "The presence of overweight/obesity was associated with age, hypertension, use of metformin, lower levels of HDL-Cholesterol, higher levels of uric acid, triglycerides, and C-reactive protein." (PMID 36823646, 2023). "Among those, IL-6 and CRP are up-regulated in parallel with adipose tissue enlargement in subjects with obesity." (PMID 36902180, 2023). "This study compared high-sensitivity CRP (hs-CRP) in adult obesity and central obesity in Indonesia based on omega-3 fatty acid intake using Indonesian Family Life Survey (IFLS) 5 data." (PMID 37754594, 2023). "Regarding fundamental conclusions, it is well known that a 75-year-old person with high levels of C-reactive protein, or diminished albumin, or with obesity, or high cholesterol, is unhealthy and has an increased risk of mortality." (PMID 37702598, 2023). "The results of the National Health and Nutrition Examination Survey 1999–2004 (USA) showed that significant obesity was related to high CRP markers of inflammation." (PMID 37627482, 2023). "More attention in the intervention of overweight and obesity should be paid to boys living in urban areas, and high serum CRP level should also be concerned." (PMID 35379317, 2022). "Factors that were related to progression versus regression were older age, higher obesity indices, higher CRP, higher HbA1C, and HOMA-IR." (PMID 35509100, 2022). "Based on our findings, patients with obesity and elevated WBC and CRP level should be considered to be at a high risk for poor clinical course in the treatment of PID." (PMID 35978309, 2022). "Recent studies have supported the use of the IL‐6R inhibitor tocilizumab, and the use of colchicine in COVID‐1947 was associated with the reduction of multiple inflammatory mediators, including CRP, IL‐6, resistin, and vascular proteins in obesity." (PMID 35837843, 2022). "We observed a significant decrease of CRP level in the GH group comparing with controls in our study of boys with obesity and NAFLD." (PMID 35216556, 2022). "The same investigators demonstrated 5 years later that increased serum levels of PTX3 positively correlate with age, obesity, systolic blood pressure, serum CRP levels, or carotid intima-media thickness (p values below 0.045 for all parameters)." (PMID 35563387, 2022). "Our study analyzes the influence of obesity-related parameters in the relationship of high-sensitivity C-reactive protein (hs-CRP) with HDL-cholesterol and HDL-phospholipid in male and female adolescents." (PMID 35217714, 2022).